SIRT1 (sirtuin 1)
Diseases named in the same sentence as SIRT1 in open-access papers (continued):
Sharing a sentence is not in itself a finding about the gene and the disease.
Sepsis (continued). "Alternatively, SIRT1 inhibitors have also been shown in pre-clinical trials to augment glycolysis and immune responses post sepsis, through a stabilization of HIF-1α55." (PMID 30446641, 2018). "We previously demonstrated disrupting SIRT1 24 h after sepsis promotes immunometabolic competence in monocytes within 6 h and markedly improves 7 day survival in septic mice." (PMID 30069485, 2018). "Specifically, SIRT1 inhibition using EX-527 during the hypo-inflammatory phase of lean mice with sepsis improved bacterial clearance, shortened hypo-inflammation and improved survival in these mice." (PMID 30216989, 2018). "In vivo experiments showed that there was a physical interaction between SIRT1 and HMGB1 in the nucleus and that SIRT1 regulated the acetylation level of HMGB1 in response to sepsis-related liver injury." (PMID 30533222, 2018). "To assess the function of the antigen-receptor following SIRT1 treatment during sepsis immune tolerance, we measured IFNγ production from total T cell antigen-receptor-stimulated T cells (including CD4+ and CD8+)." (PMID 30069485, 2018). "The experimental results indicated that SIRT1 expression should be inhibited in the later stage of sepsis." (PMID 30533222, 2018). "SIRT1 inhibits the production of pro-inflammatory cytokines in macrophages, and our group has reported that SIRT1 alleviates LPS-induced sepsis." (PMID 29867921, 2018). "This study is consistent with the unifying concept that a nuclear immunometabolic checkpoint controlled at least in part by SIRT1 directs innate and adaptive immune reprogramming during sepsis and informs molecular-based immune axis targeting." (PMID 30069485, 2018). "To explain why SIRT1 almost plays an opposite role in sepsis development, we first need to review the distinct stages of this disease." (PMID 30533222, 2018). "SIRT1 regulates immunometabolic polarity during the hyper-inflammatory and hypo-inflammatory phases of sepsis." (PMID 30216989, 2018). "They further support SIRT1 as a molecular target for deprogramming tolerance and immune repression during sepsis." (PMID 30069485, 2018). "In this study, we found that SIRT1 levels were decreased in sepsis both in vitro and in vivo and that SIRT1 regulation of Notch signaling affected inflammation." (PMID 29867921, 2018). "We further showed that chronic NAD+ generation persistently promotes SIRT1 activation in monocytes to maintain immune tolerance in monocytes in mice and human sepsis." (PMID 30069485, 2018). "It has been reported that SIRT6 and SIRT3 work closely with SIRT1 in the sepsis adaptation stage to jointly regulate energy shifts, promote mitochondrial-nuclear exchange, and accelerate the development of immunosuppression." (PMID 30533222, 2018). "SIRT1 is reported to participate in macrophage differentiation and affect sepsis, and Notch signaling is widely reported to influence inflammation and macrophage activation." (PMID 29867921, 2018). "Silent information regulator 1 (SIRT1), is a conserved deacetylase that is dependent on nicotinamide adenine dinucleotide and reportedly involved in sepsis." (PMID 30186119, 2018). "Based on the findings highlighted earlier and our previous studies on sepsis, we tried to elucidate both the role of Notch signaling during LPS-induced inflammation and the interaction of SIRT1 with Notch signaling." (PMID 29867921, 2018). "Substantial evidence shows that extreme stress response to sepsis induces remarkable drop of Sirt1 expression and hyperinflammation." (PMID 29209448, 2017). "Salidroside reduced the production of pro-inflammatory cytokines (TNF-α and IL-6) through a SIRT1-mediated inhibition of NF-κB activation pathway in the early sepsis phase." (PMID 28931916, 2017). "In the present study, salidroside treatment reversed both sepsis-induced downregulation of SIRT1 expression and increased proinflammatory cytokines (TNF-α and IL-6) secretion." (PMID 28931916, 2017).
Sepsis (continued). "Nuclear SIRT1, the most extensively studied sirtuin, epigenetically directs the pro- versus anti-inflammatory response in sepsis." (PMID 28503576, 2017). "Melatonin attenuates oxidative stress induced by sepsis via SIRT1 signaling activation in C57BL/6J mice." (PMID 28903430, 2017). "In the late sepsis phase, salidroside protected against sepsis-induced acute lung injury through the SIRT1-mediated HMGB1 nucleocytoplasmic translocation pathway." (PMID 28931916, 2017). "In the severe stress of sepsis, SIRT1 dependent control over immunometabolic reprogramming during adaptation, which counters the initial hyperinflammatory response, is prolonged." (PMID 26904696, 2016). "There is report that Sirt1 activation markedly alters transcription profiles and improves outcome in experimental sepsis, which is similar to what we observed with AnxA2." (PMID 27389701, 2016). "We show that the SIRT1 levels are increased during the hypoinflammatory (endotoxin tolerant: adaptation) phase of sepsis adaptation in mice." (PMID 26904696, 2016). "As a rheostat, low expression of SIRT-1 and other sirtuins amplify early sepsis and high expression sustain repressed immunity." (PMID 27500833, 2016). "Accordingly, SIRT1 activation before sepsis onset or preceding administration of bacterial endotoxin protects against the initial “hyperinflammation” of sepsis." (PMID 26904696, 2016). "The aim of this study was to determine the role of SIRT1/3 in acute kidney injury (AKI) following sepsis in a septic rat model." (PMID 28003866, 2016). "Calorie restriction with increased SIRT1 improves outcome in polymicrobial sepsis in mice via activation of SIRT1." (PMID 26904696, 2016). "Based on their results, they claimed that SIRT1 inhibition repressed bioenergetics during sepsis adaptation and finally improved survival time." (PMID 28003866, 2016). "Interestingly, SIRT1 activity is decreased in the liver, spleen, small bowel, and lung tissue in experimental sepsis models, and SIRT1 activation could improve the outcome of sepsis and ameliorate the associated inflammatory response." (PMID 28003866, 2016). "In this study, we demonstrated that SIRT1 protein levels and activity in kidney tissue progressively declined in the early phase (−8 h) of sepsis." (PMID 28003866, 2016). "More recently, we observed that the resveratrol-mediated inhibition of HMGB1 nucleo-cytoplasmic translation in sepsis-induced liver injury depends on SIRT1-mediated deacetylation." (PMID 26525891, 2015). "Taken together, these findings collectively suggest that SIRT1 is an important regulator in many high glucose-related inflammatory diseases such as sepsis." (PMID 25793995, 2015). "SIRT1 overexpression significantly improved mouse survival rates (46%) after CLP-induced sepsis, compared with control LacZ expressing adenovirus-injected mice (13%) as determined on day 6 (lower) (log-rank test, P < 0.05)." (PMID 24573134, 2014). "Our results showed that Sirt1 deletion led to increased LPS-induced IL-6 and TNF-α production, suggesting that Sirt1 acts to suppress inflammatory responses during sepsis." (PMID 24896770, 2014). "In this study, we demonstrated that SIRT1 expression inhibits LPS-induced secretion of proinflammatory cytokines and protects against endotoxemia and sepsis." (PMID 24573134, 2014). "This is the first report demonstrating the mechanism of SIRT1 expression in LPS-induced inflammatory reactions and the protective effect of SIRT1 on endotoxemia and sepsis." (PMID 24573134, 2014). "Our work suggests that both SIRT1 and SIRT1-inducing cytokines are useful targets for treating patients with sepsis." (PMID 24573134, 2014). "Our studies indicate that Sirt1 is a potential therapeutic target to treat sepsis-induced kidney injury." (PMID 24896770, 2014).
Sepsis (continued). "Even though it will be intriguing to link uncontrolled inflammatory responses in the elderly during sepsis to the reduced Sirt1 expression, more studies are needed to elucidate the role of Sirt1 in aging-related kidney injury." (PMID 24896770, 2014). "To determine whether 3,4‐cPP affects SIRT1 expression in endothelial cells, another central sepsis target, we assessed the effect of 3,4‐cPP using murine yolk sac endothelial cells (MYSECs)." (PMID 40470379, 2025). "In another study, EVs from endothelial progenitor cells encapsulated TUG1 to stimulate M2 macrophage polarization and inhibited inflammation by suppressing miR-9-5p to upregulate SIRT1 expression, which prevented the development of sepsis and alleviated sepsis-induced renal damage." (PMID 40332144, 2025). "Thus, 3,4‐cPP, an S1P1/SIRT1 activator, is a potential candidate for treating sepsis and related complications, including ARDS." (PMID 40470379, 2025). "Additionally, SIRT1 relieves sepsis by inhibiting glycocalyx degradation, thereby normalizing vascular permeability." (PMID 40470379, 2025). "In sepsis, SIRT1 accumulates at IL‐1β/TNF‐α promoters with NAD+‐enhanced H3K16 deacetylation." (PMID 41208649, 2025). "Furthermore, SIRT1 inhibition by EX-527 reversed the effects of NMN-induced M2 macrophage polarization sepsis-induced acute lung injury." (PMID 40698661, 2025). "Additionally, resveratrol, the SIRT1 activator, can prevent sepsis and its related complications in several ways." (PMID 40698661, 2025). "Mitotherapy involving repetitive injections after CLP led to a restoration of gene expression levels of SIRT-1 (P=0.0262 vs Sepsis group), PGC-1α (P=0.0191 vs Sepsis group), and Mfn2 (P=0.0175 vs Sepsis group), bringing them closer to the levels observed in the pre-damage state." (PMID 40584438, 2025). "Hence, SIRT1 is an essential target for sepsis treatment that can simultaneously inhibit immunosuppression and vascular permeability." (PMID 40470379, 2025). "Evidence suggest a beneficial role of Sirt1 activation in the context of sepsis." (PMID 41096578, 2025). "Additionally, in a rat model of peritonitis, resveratrol, another SIRT1 activator, provided protection against sepsis-induced liver injury." (PMID 41096578, 2025). "Resveratrol, a known SIRT1 activator, effectively restore the activity of SIRT1/3 in sepsis rats with AKI, reduce the acetylation levels of recombinant superoxide dismutase 2 (SOD2), improve oxidative stress and mitochondrial function in renal tubular epithelial cells, and extend survival time." (PMID 40989844, 2025). "Previous studies have suggested that SIRT1 activation may reduce endothelial permeability and ROS production in models of LPS-induced injury, but this requires confirmation in pneumonia and sepsis." (PMID 41096578, 2025). "Drug induction of autophagy via SIRT1-mediated Beclin-1 deacetylation may represent a promising therapeutic approach for sepsis treatment in the future." (PMID 40766066, 2025). "Sirt1 is downregulated in macrophages from mouse models of sepsis or upon LPS stimulation." (PMID 41096578, 2025). "Similarly, in sepsis-induced cardiac insufficiency, relief can be observed through Sirt1-mediated Beclin-1 deacetylation and autophagy." (PMID 40766066, 2025). "SIRT1 mediates protection against endothelial damage during sepsis and endotoxemia." (PMID 40470379, 2025). "The team believes that NMN promotes macrophage polarization through the SIRT1/NF-κB pathway to prevent sepsis-induced acute lung injury, which may be an effective strategy for preventing or treating sepsis-induced acute lung injury." (PMID 39411062, 2024).
Sepsis (continued). "SIRT5 and SIRT1/2 have opposite expression patterns and functions in macrophages during sepsis." (PMID 39372420, 2024). "NMN protects against sepsis-induced ALI by promoting M2 macrophage polarization via the SIRT1/NF-κB pathway, it might be an effective strategy for preventing or treating sepsis-induced ALI." (PMID 38100537, 2024). "This suggested that taraxerone may serve as a potential drug targeting SIRT1 for the treatment of sepsis-induced acute lung injury." (PMID 39543653, 2024). "However, Mel protected against sepsis-induced cardiac dysfunction by increasing autophagy via activation of SIRT1." (PMID 38195474, 2024). "However, the protective effects of melatonin were nullified upon administering the SIRT1 specific inhibitor EX-527, providing compelling evidence for melatonin’s role in mitigating sepsis-induced brain damage through the activation of SIRT1 signaling." (PMID 38690282, 2024). "Herein, we speculated that the SIRT1/NF-κB axis is responsible for the protective effect of NMN against sepsis-induced ALI." (PMID 38100537, 2024). "Additionally, it regulates the transcription of SIRT1 by modulating the interaction between microRNA-9 and the 3’-untranslated region of SIRT1 mRNA, thereby mitigating the inflammatory response and sepsis-induced liver damage." (PMID 38690282, 2024). "miR-199a can target the regulation of SIRT1 in alveolar macrophages, and its downregulation may protect against sepsis-induced lung injury by upregulating SIRT1 through inhibition of excessive inflammatory responses and suppression of apoptosis in lung tissue." (PMID 38690282, 2024). "Therefore, curcumin promotes mitochondrial biogenesis and inhibits mitochondrial fragmentation by activating SIRT1, thereby improving the mitochondrial quality and reducing oxidative stress in cardiomyocytes and sepsis-induced cardiac dysfunction." (PMID 38586339, 2024). "NMN can effectively ameliorate sepsis-induced ALI through modulating macrophage polarization via SIRT1/NF-κB signalling pathway, which may provide a novel therapeutic direction for treating acute lung injury." (PMID 38100537, 2024). "However, during the hypo-inflammatory phase of sepsis, SIRT1 inhibition by EX-527 represses adhesion molecule expression in MECs while stabilizing blood pressure and microvascular perfusion." (PMID 39598406, 2024). "For example, activation of SIRT1 has been reported to have a beneficial effect in the initial (proinflammatory) phase, whereas SIRT1 expression should be reduced in the later stages of sepsis." (PMID 36769283, 2023). "Moreover, in a recent report, PD was demonstrated to protect against mitochondrial dysfunction and NLRP3 inflammasome activation in sepsis-induced acute kidney injury by activating Parkin-dependent mitophagy via the activation of sirtuin 1 (SIRT1)." (PMID 37112536, 2023). "SIRT1 activation improved sepsis AKI by promoting Beclin1-mediated autophagy." (PMID 37215112, 2023). "SIRT1 levels are suppressed in sepsis mice compared to normal mice." (PMID 38001778, 2023). "Thus, the objective of this study was to explore the in vivo effects of echinacoside mediated by the SIRT1-regulated NOX4-Nrf2 axis on ALI induced by sepsis, as well as its in vitro effects on endothelial cells stimulated by LPS." (PMID 38001778, 2023). "Emodin inhibits SIRT1-mediated HMGB1 protein expression by increasing the mRNA and protein expression of VDR and its downstream molecules, thus alleviating the lung injury caused by sepsis." (PMID 37628912, 2023).
Sepsis (continued). "Therefore, this study aimed to investigate the effects of echinacoside on sepsis-induced acute lung injury and oxidative stress in mice and to explore the intricate regulatory mechanism of SIRT1 on NOX4." (PMID 38001778, 2023). "Moreover, ginsenoside Rg3 can alleviate sepsis-related hepatic injury through modulation of TUG1/miR-200c-3p/SIRT1 axis." (PMID 37441551, 2023). "In sepsis, upregulation of miR-181a, miR-133a and miR-195 has been shown to lead to downregulation of SIRT1 and aggravation of inflammatory responses." (PMID 37441551, 2023). "Third, only CLP was used to establish an SAE model in this study, and the activation of the Fgr/SIRT1/PGC-1α pathway may play a different role in sepsis induced by other factors." (PMID 37475042, 2023). "The variation in the observed effects of SIRT1 in sepsis may be due to the different treatment times of SIRT1; that is, SIRT1 needs to be treated according to the different stages of the disease." (PMID 37475042, 2023). "The role played by the deacetylase SIRT1 in sepsis also received wide recognition." (PMID 36774341, 2023). "Similarly, SIRT1 mediates the protective effects of echinacoside in attenuating ROS-mediated endothelial cell mitochondrial apoptosis, thereby alleviating sepsis-induced acute lung injury in mice." (PMID 38001778, 2023). "In addition, SIRT1 attenuated sepsis-induced AKI by activating Beclin1 deacetylation-mediated autophagy." (PMID 35277012, 2022). "Syringaresinol ameliorated sepsis-induced cardiac dysfunction via the ER/SIRT1/NLRP3/GSDMD pathway." (PMID 35509275, 2022). "On the other hand, SIRT1 regulation of the immunosuppression phase of sepsis remains uncertain." (PMID 35359990, 2022). "Thus, the effects of SIRT1 on NF-κB renders SIRT1 important to the study of inflammatory diseases including sepsis." (PMID 35359990, 2022). "In general, the conclusions drawn from these reports are consistent with the results in our research, that is, Hmox1, Epas1, Sirt1, Slc3a2, Jun, Plin2 and Zfp36 collectively promote the development of sepsis-induced liver failure by interacting with B cells and NK cells." (PMID 35923893, 2022). "miR-197 contributed to LPS-induced cardiomyocyte injury by modulating SIRT1, which might be used as a molecular marker in the management of sepsis." (PMID 35223094, 2022). "Furthermore, the mechanism by which NAD+/SIRT1 alleviates the sepsis‐induced AKI involves the regulation of glycogen synthase kinase‐3β (GSK‐3β) / nuclear factor erythroid 2‐related factor 2 (Nrf2) signalling pathway." (PMID 35137552, 2022). "In the study of sepsis, the expression of SIRT1 was found to be significantly reduced in the myocardial tissue of septic mice, and activation of SIRT1 could evidently ameliorate cardiac dysfunction caused by perforation of appendix ligation." (PMID 35223094, 2022). "Accumulating studies have confirmed the protective role of SIRT1 in treatment of sepsis." (PMID 35359990, 2022). "For example, in LPS-stimulated H9c2 cardiomyocytes, SIRT1 mRNA and protein levels were both significantly upregulated, and cardiac tissues harvested from sepsis mice in the cecal ligature and puncture (CLP) model showed that SIRT1 expression was increased in sepsis." (PMID 35359990, 2022). "It has also been reported that SIRT1 contributed to sepsis by regulating autophagy." (PMID 36030287, 2022). "Therefore, we screened the ferroptosis-related genes (Hmox1, Epas1, Sirt1, Slc3a2, Jun, Plin2 and Zfp36) in this study through bioinformatics analysis, and found that these genes were highly expressed in sepsis-induced liver failure model." (PMID 35923893, 2022). "It has been reported that miR-133a in sepsis can target SIRT1 to aggravate inflammation." (PMID 35279129, 2022). "In this study, we examined that the role of NAD+/SIRT1 in sepsis‐induced AKI." (PMID 35137552, 2022). "Sepsis-induced ALI was attenuated by miR-199a via targeting of sirtuin 1 (SIRT1)." (PMID 35986232, 2022).